ALB (albumin)
Diseases named in the same sentence as ALB in open-access papers (continued):
Sharing a sentence is not in itself a finding about the gene and the disease.
sarcopenia (continued). "In the field of nutrition, the scientific community openly acknowledges haemoglobin, albumin, leptin, uric acid, iron, and vitamin D, amongst others, in predicting the risk of sarcopenia." (PMID 37110223, 2023). "Myosteatosis and concurrent myosteatosis and sarcopenia were associated with proximal tumor location (p = 0.021), serrated morphology (p = 0.002), and lower albumin level (≤35 g/L)." (PMID 35566781, 2022). "In a meta-analysis, a significant association was found between low ALB levels and sarcopenia in adults 60 years of age and older." (PMID 35370985, 2022). "First, prolonged hospital stay in the sarcopenia group was significantly associated with serum albumin levels and CPB time." (PMID 35313647, 2022). "Sarcopenia was the most influential factor of postoperative hospital stay; in addition, preoperative albumin level and CPB time were the independent factors associated with the length of postoperative hospital stay." (PMID 35313647, 2022). "Third, apart from the outcomes concerning sarcopenia, primary tumor growth and decreased albumin were found to be independent predictors of a higher risk of mortality in this study." (PMID 35023149, 2022). "Sarcopenia was associated with lower BMI and lower serum albumin levels (when reported) in almost all these references, and was more frequent in patients ≥ 60 years old in one study." (PMID 36568174, 2022). "With the exception of albumin, the skeletal muscle protein biomarkers were significantly associated with the risk of sarcopenia (Models 1–3)." (PMID 35453410, 2022). "In the univariate analysis, nutritional parameters including serum albumin ≥ 40 g/L, non-sarcopenia, TNM stage I-II and N stage 0–1 were strongly associated with an improved OS." (PMID 35501704, 2022). "The implications of inflammation, sarcopenia, vitamin D deficiency and albumin, as dimensions inherent in fragility, in the development and setting of chronic coronary syndromes (CCSs) have proven their patent significance but are still open to research." (PMID 36013312, 2022). "Sarcopenia was associated with being older; inflammation; poorer renal function; and lower serum albumin, total testosterone, and haemoglobin." (PMID 33949807, 2021). "Sarcopenia was associated with low serum albumin (p = 0.02) and low serum phosphate level (p = 0.04)." (PMID 34579163, 2021). "The results obtained from the model suggest that advanced age, sarcopenia, and low serum albumin levels are high risk factors for a poor functional outcome." (PMID 34912895, 2021). "Our predictive model is effective in predicting the risk of poor functional prognosis after patellar fracture surgery in the elderly by assessing high-risk factors such as advanced age, sarcopenia, and serum albumin levels." (PMID 34912895, 2021). "The differences in risk factors (e.g. CRP, albumin, and testosterone) between those with and with sarcopenia should be treated cautiously." (PMID 33949807, 2021). "The results of the logistic regression analysis showed that age, BMI, JST-IC representing higher-level functional capacity, and serum albumin level reflecting nutritional and inflammatory status were significantly associated with sarcopenia." (PMID 34205795, 2021). "On univariate analysis, the following nine factors were associated with sarcopenia: age, BMI, LC, albumin, IGF-1, BCAA, osteoporosis, prevalent fracture, and high fracture risk." (PMID 34575191, 2021). "The prevalence of sarcopenia increased even when other risk factors were considered, especially in patients with low serum albumin levels." (PMID 34531464, 2021). "Although there are studies exploring the association between albumin and sarcopenia, there is a need to continue evaluating its association with biological markers and comparing them to verify which can be used to detect sarcopenia among the elderly." (PMID 34559500, 2021).
sarcopenia (continued). "In patients with eGFR < 45 mL/min/1.73 m2, total cholesterol and serum albumin showed significant associations with sarcopenia, even if the parameters were adjusted." (PMID 34531464, 2021). "Sarcopenia affected 18% of our dialysis population, where low serum albumin and phosphate levels were associated risk factors." (PMID 34579163, 2021). "A logistic regression showed oral hypofunction, age, body mass index, higher-level functional capacity, and serum albumin level were significantly associated with sarcopenia." (PMID 34205795, 2021). "We identified that low serum albumin and phosphate levels were significantly associated with sarcopenia in our dialysis population, while there was also a trend showing age being associated with sarcopenia." (PMID 34579163, 2021). "This review synthesizes the knowledge on the association between sarcopenia and serum albumin among elderly individuals through a systematic review and meta-analysis focused on the etiology and risk factors." (PMID 34559500, 2021). "The progression of sarcopenia in T2D patients has been associated with lower renal function and higher urinary albumin levels." (PMID 32405506, 2020). "Multivariate survival analysis using backward stepwise selection revealed that early postoperative mortality was associated with preoperative sarcopenia, metastatic disease, and preoperative albumin level." (PMID 32238149, 2020). "The univariate analysis showed that the following eight variables were significantly associated with sarcopenia: age, BMI, LC, serum levels of albumin, BCAA, and 25(OH)D, PT-INR deficiency vitamin D." (PMID 33322706, 2020). "In LC-cases, univariate analysis identified four factors to be significantly associated with the presence of sarcopenia: age (P = 0.0026), BMI (P = 0.0010), serum albumin (P = 0.0035), and our classification of serum zinc concentration (P = 0.0016)." (PMID 30862022, 2019). "Sarcopenia has previously been reported to be associated with declining renal function, leading to lower glomerular filtration rate and higher urine albumin to creatinine ratio." (PMID 31035928, 2019). "Sarcopenia was associated with sex (p<0.001), weight loss (p = 0.02), lower albumin levels (p = 0.011), higher tumor grading (p = 0.023) and neoadjuvant therapy (p = 0.035)." (PMID 31059520, 2019). "Sarcopenia was significantly associated with urinary albumin level with a pooled OR of 2.11 (95% CI, 1.55–2.88; P < 0.001)." (PMID 31828155, 2019). "Multivariable linear regression analyses were performed to assess the associations between erythrocyte sedimentation rate, albumin, white blood cell count and measures of sarcopenia." (PMID 31455238, 2019). "Sarcopenia was significantly associated with urinary albumin level, urinary protein level, and decreased eGFR." (PMID 31828155, 2019). "Albumin was found to be associated with two measures of sarcopenia: gait speed and handgrip strength." (PMID 31455238, 2019). "Other studies have demonstrated the effects of sex on the association between sarcopenia and decreased renal function (urinary albumin level and the duration of kidney disease)." (PMID 31828155, 2019). "Data were extracted from studies investigating the association between sarcopenia and urinary albumin level, urinary protein level, and eGFR and by calculating odds ratio (OR) and 95% confidence intervals (CIs)." (PMID 31828155, 2019). "A previous study based on the national health survey data demonstrated that OR of the association between sarcopenia and urinary albumin level was approximately 1.63–2.34, indicating a significant association." (PMID 31828155, 2019). "Sarcopenia subjects had higher nutrition risk but lower body mass index (BMI), serum albumin (ALB), triglyceride (TG), and creatinine (Cr) levels compared to non-sarcopenia subjects." (PMID 30541467, 2018). "In the present study, low albumin was associated with sarcopenia, low muscle mass and low grip strength." (PMID 28902873, 2017).
sarcopenia (continued). "Traditional oncological therapies and perioperative nutritional assessments that focus on weight loss and markers such as serum albumin have overlooked sarcopenia as a determinant of prognosis after oncological surgery." (PMID 27800156, 2016). "Previous research has found that low albumin levels may be an important risk factor for sarcopenia, and that albumin values are correlated with decreased muscle strength." (PMID 41446845, 2025). "However, when ALB < 40 g/L (normal range: 35 to 50 g/L), the risk of sarcopenia increases by 3.6 times, which is consistent with the report of Japanese scholars." (PMID 39910436, 2025). "Furthermore, lower serum albumin levels, which reflect liver synthetic function, have also been implicated in the pathogenesis of sarcopenia." (PMID 40686817, 2025). "Viewed as a key marker of nutritional health, albumin might contribute synergistically to the heightened risk of adverse events associated with sarcopenia." (PMID 40988472, 2025). "Additionally, studies have shown that low albumin levels in CKD increase the risk of sarcopenia, a hallmark of frailty." (PMID 40283583, 2025). "As a result, this decrease in albumin in old age is highly associated with sarcopenia risk." (PMID 39096855, 2024). "Secondly, albumin was negatively and linearly associated with the risk of sarcopenia." (PMID 39096855, 2024). "Reduced LBM, indicative of sarcopenia, was associated with markers of nutritional status, with lower baseline haemoglobin (P < .001), haematocrit (P < .001), albumin (P = .044), and reduced protein metabolism, as indicated by urea (P = .017) and creatinine (P < .001)." (PMID 37861366, 2024). "Our study highlights sarcopenia as a significant concern in older adult inpatients, with a high prevalence and a clear association with worse OS, particularly among those with additional risk factors such as metastasis and low albumin levels." (PMID 39104037, 2024). "In a multivariate analysis, sarcopenia was significantly associated with extensive ileal disease (OR = 5.58; 95% CI, 1.03–30.20; p < 0.005), low serum albumin (OR = 0.11; 95% CI, 0.01–0.78; p < 0.03), and a small waist circumference (OR = 0.69; 95% CI, 0.54–0.89; p < 0.005)." (PMID 39683376, 2024). "Specifically, frail older people are characterized by reduced gastric motility and liver metabolism, sarcopenia, (ie, loss of skeletal muscle mass and strength as a result of low-grade inflammation), decreased lean body mass, lower albumin levels and reduced renal function." (PMID 38595957, 2024). "Additionally, metabolically unhealthy status, HbA1c, vitamin D and albumin levels partially mediated the association between sarcopenia and MUI, as well as between sarcopenic obesity and SUI or MUI." (PMID 39469327, 2024). "Additionally, our cohort revealed that sarcopenia was linked to advanced age, serum albumin levels, and CRP levels, aligning with earlier studies." (PMID 39315011, 2024). "In addition, being married and having an adequate albumin concentration were associated with a decreased risk of sarcopenia in the study sample." (PMID 37363476, 2023). "Additionally, serum albumin levels are indicators of sarcopenia in older adults; FD is reportedly associated with low serum albumin levels." (PMID 37355574, 2023). "The current study investigated whether undernutrition status, as assessed by GNRI, CONUT, and albumin, is associated with the diagnosis of sarcopenia and its components." (PMID 36819693, 2023). "Sarcopenia and low albumin level were significantly associated with an increased rate of delayed neutropenia after HIPEC in that disease setting and could be the preoperative risk predictors." (PMID 36814253, 2023). "Along with BMI, albumin was the most important factor associated with osteosarcopenia, indicating how a balanced protein profile is crucial for preventing the onset of both osteoporosis and sarcopenia." (PMID 37960189, 2023).
sarcopenia (continued). "Given that sarcopenia and low serum albumin levels are reported risk factors for poor prognosis in HD patients, whole blood SPM/SPD in hemodialysis patients may be a new indicator of the prognosis and health status of HD patients." (PMID 36979725, 2023). "Increased NLR might reduce albumin levels, resulting in sarcopenia caused by weakened skeletal muscles." (PMID 36895911, 2023). "Therefore, an additional RF plot was built without splitting the two samples to get a selection of variables most associated with sarcopenia, and found that albumin, CRP, and folate ranked high." (PMID 37110223, 2023). "The presence of sarcopenia associated significantly with albumin, haemoglobin and CRP." (PMID 37906352, 2023). "This study showed that sarcopenia and low albumin level were significantly associated with an increased rate of neutropenia in patients undergoing HIPEC combined surgery for gastrointestinal cancers and could be used in preoperative risk prediction." (PMID 36814253, 2023). "The impaired albumin production imposed by liver dysfunction may thus mask the association between albumin and sarcopenia." (PMID 36248997, 2022). "The sarcopenia/obesity group was associated with older age, a higher proportion of men, and a higher proportion of frail patients, as well as higher levels of haemoglobin, haematocrit, serum albumin, total cholesterol, and triglycerides." (PMID 35787667, 2022). "In other respects, high doses of albumin can reduce the risk of sarcopenia." (PMID 35544482, 2022). "Serum albumin is associated with skeletal muscle, and sarcopenia and low albumin may synergistically increase the risk of incident disability in older adults." (PMID 35453410, 2022). "Lower levels of total protein and albumin were linked to sarcopenia and cognitive impairment." (PMID 35805838, 2022). "Creatinine concentration is affected by lean body mass whereas low albumin level is predictive of poor muscle mass and may increase the risk of sarcopenia in the elderly." (PMID 35223061, 2022). "Furthermore, sarcopenia and low serum albumin levels synergistically increase the risk of disability in older adults." (PMID 36551629, 2022). "Moreover, low hemoglobin and albumin levels were at risk of poor nutritional status and contributed to the development of sarcopenia." (PMID 35804906, 2022). "In addition, age, BMI, JST-IC score, and serum albumin level were significantly associated with sarcopenia." (PMID 34205795, 2021). "Albumin levels tend to decrease with age, and this effect seems to imply an increased risk of complications and higher rate of mortality, morbidity, and disabilities such as sarcopenia and frailty." (PMID 33800577, 2021). "Instead, the association between serum albumin levels and sarcopenia remains significant." (PMID 34531464, 2021). "This approach could facilitate a quantitative study of variables such as lymphopenia, albumin, glucose control, sarcopenia, and weight loss in relation to clinic days, hospital days, documented infections, disease-free survival, and overall survival." (PMID 34959948, 2021). "However, only 5% of UH in our series were due to toxicity, which suggests that the association with albumin and weight loss rather indicates frailty or sarcopenia." (PMID 35008291, 2021). "In addition, vitamin D in pediatric patients, as well as hemoglobin and albumin in adult patients have been associated with sarcopenia." (PMID 32784808, 2020). "In addition, female gender, liver dysfunction, and a low albumin level are risk factors for sarcopenia." (PMID 33014288, 2020). "Interestingly, we found a strong association of sarcopenia with neoadjuvant therapy, poor tumor differentiation and low serum albumin levels; all of these factors are known to further promote physical deterioration." (PMID 31059520, 2019). "The results showed a significant association between sarcopenia and urinary albumin level." (PMID 31828155, 2019).
sarcopenia (continued). "The results demonstrated a significant association between sarcopenia and urinary albumin level." (PMID 31828155, 2019). "The impacts of clinicopathologic features, including age, sex, histologic type, albumin, C-reactive protein, body mass index, pretreatment sarcopenia, weight loss rate, skeletal muscle change, and pathologic stage, on OS were evaluated using multivariable analysis." (PMID 28861809, 2017). "Albumin declines during aging and is associated with sarcopenia." (PMID 27191382, 2016). "On the contrary, low BMI may indicate cachexia, with associated sarcopenia and low albumin levels." (PMID 41228215, 2025). "However, our results showed that serum albumin was not an independent risk factor for POD after gastrointestinal cancer surgery, which might be related to the effect of sarcopenia on modifying the serum albumin/POD association." (PMID 39144259, 2024). "Interestingly, sarcopenia is also associated with a low preoperative serum albumin level." (PMID 36769619, 2023). "Albumin is considered a critical indicator of nutritional status, and it may potentially synergistically contribute to an increased risk of adverse events in association with sarcopenia." (PMID 37810784, 2023). "In addition, we report low serum albumin and phosphate levels were associated with sarcopenia." (PMID 34579163, 2021). "The association between having fewer teeth and a lower protein (specifically, animal protein) intake as well as lower serum albumin levels is a notable finding, because a low serum albumin level may be a modifiable risk factor for frailty, sarcopenia, and mortality in older people." (PMID 30611201, 2019). "Interestingly, these factors have also been reported as those contributing to sarcopenia, suggesting that sarcopenia may be associated with urinary albumin level, urinary protein level, and decreased eGFR." (PMID 31828155, 2019). "This study aimed to evaluate the impact of sarcopenia and preoperative albumin on postoperative management outcomes and resource utilization in CEA patients with a high prevalence of metabolic comorbidities." (PMID 42122080, 2026). "In our study, the albumin levels were found to be significantly lower in the sarcopenia group (31.1 ± 5.9 g/dL)." (PMID 40005385, 2025). "Sarcopenia also correlated with lower albumin levels, a higher prevalence of ischemic stroke, and increased mechanical ventilation needs." (PMID 40005385, 2025). "Low ALT was significantly associated with an increased incidence of other markers of frailty and sarcopenia such as low albumin (14% vs. 1.6%, p < 0.001) and low creatinine (0.2% vs. 0.005%, p ≤ 0.001)." (PMID 40837240, 2025). "Patients with sarcopenia had significantly lower BMI, lower serum albumin, and reduced T-scores of the lumbar spine compared to those without sarcopenia." (PMID 41343088, 2025). "Six optimal predictors were identified: underweight, sarcopenia, poor performance status, midstream urine culture, urinary leukocyte count, and albumin-globulin ratio (AGR)." (PMID 40065041, 2025). "Concurrently, the application of ML methods to clinical data identified significant markers of sarcopenia, including albumin, C-reactive protein (CRP), folate, and vitamin D." (PMID 41303670, 2025). "We demonstrated for the first time that nutritional frailty, expressed by high E-DII, was closely related to high CRP/albumin ratio in sarcopenia and probable sarcopenia." (PMID 41345186, 2025). "Nevertheless, further studies are still needed to explain epidemiological and clinical significance of CRP/albumin ratio in predictions of sarcopenia and the survival of old elderly adults in conjunction with the nutritional status." (PMID 41345186, 2025). "A meta-analysis shows that gender, low BMI, age, and low albumin levels significantly affect the occurrence of sarcopenia in adult patients with CD." (PMID 41190159, 2025).